IL10 (interleukin 10)
Diseases named in the same sentence as IL10 in open-access papers (continued):
Sharing a sentence is not in itself a finding about the gene and the disease.
tumor (continued). "The expressions of IL-10 mRNA in tumor tissues among groups displayed a similar trend as that of WTAP, which verified the correlation between WTAP expression and immunosuppression in our xenograft animal model." (PMID 34081626, 2021). "Several studies have shown that IL-10 leads to tumor progression due to its ability to downregulate the immune system." (PMID 34832887, 2021). "The expression of IL-10 is a prognostic factor of NSCLC, and high IL-10 expression of TAMs is an important independent predictor of advanced tumor stage." (PMID 34079469, 2021). "Herein we further demonstrated that the production of IL-10 in BI-ALCL is predominantly intrinsic to CD30-positive tumor cells, as shown by in situ hybridization data on seroma and xenograft." (PMID 33146828, 2021). "Several essential cytokines were also higher in the high-risk group, such as CCL5 (recruiting MDSC to tumor site), CCL22 (driving Treg recruitment into tumor site), and IL-10 (inhibiting cytokine synthesis)." (PMID 34961815, 2021). "In cancer, IL-10 was reported to have paradoxical effects in that both tumor-promoting and tumor-suppressive effects have been observed." (PMID 33708198, 2021). "M1 macrophages secrete higher levels of interleukin (IL)-12 and lower level of IL-10, and thereby contribute to the anti-tumor immune response." (PMID 33413474, 2021). "The presence of other cytokines, including IL‐10, sialomucins and prostaglandin E2, which have been shown to protect tumor cells against T‐cell cytotoxicity, should be investigated." (PMID 34188916, 2021). "It has been reported that inhibition of CTLA-4 induces anti-tumor activity through decreasing IL-10 secretion." (PMID 33628584, 2021). "In parallel with mobilization of Tregs, MDSCs can also convert macrophages to type 2 phenotype through releasing increased level of IL-10, thereby promoting tumor progression." (PMID 34336860, 2021). "DCs in the tumor microenvironment show phenotypic and functional alterations such as a reduced IL-12/IL-10 ratio and an impaired capability of stimulating T cells, although the expression of costimulatory molecules was increased." (PMID 33141285, 2021). "The expression profile of instructive cytokines in TIDCs from untreated tumor mice displayed a reduced IL-12/IL-10 quotient, which predicts a compromised Th1/Tc1 polarization of T-cell responses." (PMID 33141285, 2021). "IL10 is an immunosuppressive and tumor promoting cytokine expressed by subsets of T cells and myeloid cells e." (PMID 33786638, 2021). "In tumor biology, macrophages tend to differentiate into the M2 type rather than the tumor-killing M1 phenotype and produce cytokines such as IL-10, IL-4, and IL-13, which can promote tumor progression." (PMID 34148033, 2021). "Data from phase I/II clinical trials demonstrated that recombinant PEGylated IL-10 alone shows some anti-tumor effects against multiple cancer types including renal carcinoma, melanoma, and breast cancer." (PMID 34769278, 2021). "They further outlined an association between cytokine/chemokine expression and immune tumor infiltrates, suggesting that the expression of specific tumor cytokines (IFNγ, IL10, TGFβ) represents important biomarkers of melanoma immune response." (PMID 33810032, 2021). "Tumor-associated macrophages release several factors, including interleukin (IL)-6 and IL-10, which promote tumor cell growth, facilitate angiogenesis, and suppress the anti-tumor functions of other immune cells." (PMID 33618763, 2021). "For certain genes (Il10, Csf3, Cxcl1, Ccl2, Gata3, Il5, and Il13), there was a clear difference between the EC and HC Shb KO effects using Cdh5-CreERt2 or Vav1-Cre tumor-bearing mice, indicating that these effects reflect EC cell autonomy of Shb gene deletion." (PMID 34768912, 2021). "M-MDSCs inhibit IL-12 production from macrophages while stimulating IL-10 which leads to a shift from M1 to M2 TAMs to further decrease immune response and facilitate tumor progression." (PMID 35127700, 2021).
tumor (continued). "In malignant tumors, IL-10 can be secreted by T regs into the tumor microenvironment and adjacent lymph nodes, subsequently weakening local anticancer immunity." (PMID 34422050, 2021). "When tumor-delivered exosomes are in touch with immune cells, they carry IL-10 and TGF-β that enhance Treg expansion and increase expression of CTLA-4 on Tregs to promote immune suppression in melanoma." (PMID 34806028, 2021). "In these zones, IL-10 is also an important determinant of alternative M2 activation and sustainment of tumour cell proliferation." (PMID 33484377, 2021). "Certain subsets of these tumour-infiltrating Breg cells can upregulate PD-1 expression in response to signaling from cancer cells, promoting T-cell dysfunction via IL-10 or, independently of IL-10, via PD-L1." (PMID 34572910, 2021). "Although the combination therapy in our study ultimately resulted in prolonged survival in the murine tumor models, we shouldn’t neglect the contradictory role of IL-10 in CD8+T cells." (PMID 33717103, 2021). "In contrast, M2-like TAMs are induced by Th2 cytokines such as IL-4, IL-10, IL-13, and/or M-CSF, and can favor tumor growth and promote TME remodeling by producing growth factors, immunosuppressive factors, pro-angiogenic molecules, and proteases." (PMID 34603327, 2021). "Mechanistically, the S1PR1 receptor activates TGF-β signaling pathway results in TGF-β and IL-10 secretion from tumor cells." (PMID 35201458, 2021). "Monocytes and lymphocytes are the primary source of IL-10, and reports on the role of IL-10 in tumor progression are controversial." (PMID 33717103, 2021). "Many of the immunosuppressive factors produced by MDSCs that contribute to effector T-cell suppression such as TGF-β, VEGF, IL-10, and IL-6 are shown to induce a stem-like phenotype in various tumor cells." (PMID 34065010, 2021). "The combination of anti-IL-10 with anti-PD-1 treatment in this model significantly inhibits tumor growth compared to treatment with either component alone." (PMID 34769278, 2021). "Recent study has shown that environmental factors, including commensal bacteria and diet, and tumor immunosuppressive cytokines, including IL-10 and TGF-β, affect the production of IgA." (PMID 34868013, 2021). "TILs and TAMs have anti-inflammatory phenotypes and either secrete or induce factors that promote immunosuppression and tumor invasion, such as interleukin-10 (Il-10), TGF-β, PD-1, reactive oxygen species (ROS) and arginase." (PMID 34715874, 2021). "The complex regulation process results in pleiotropic biological activity of IL-10, which plays a dynamic role in the tumor microenvironment." (PMID 33628584, 2021). "Of note, inactivation of STAT3 in regulatory B-cells reduces IL10 and TGFβ production, and augments anti-tumor immunity by enhancing cytotoxic T-cell activity and by decreasing the number of Tregs in draining lymph nodes and tumor tissues." (PMID 34944848, 2021). "Treg cells treated with αGITR displayed decreases in anergic phenotype in all three tumor models as measured by the expression of Helios and the production of IL-10." (PMID 33976133, 2021). "Tumor-infiltrating DCs from mice having received therapy showed an upregulation of costimulatory molecules as well as an augmented IL-12/IL-10 ratio as compared to untreated controls." (PMID 33141285, 2021). "Conversely, M2 macrophages promote tumor development by producing anti-inflammatory cytokines, such as IL-4, IL-10, IL-13, and TGFβ, providing an immunosuppressive microenvironment that promotes tumor immune escape." (PMID 33406733, 2021). "On neighbor cells, IL-10 also hampers the maturation of dendritic cells (DCs), which are indispensable for active tumor immunity." (PMID 34572013, 2021). "One month after treatment, the IL-10 level dropped to normal with complete vitreous tumor clearance in both eyes." (PMID 33968786, 2021).
tumor (continued). "M2 TAMs secrete pro-tumor factors (IL-4, IL-6, IL-10, IL-13, EGF, and VEGF), while tumor suppressor M1 TAMs express antitumor factors (IL-12, major histocompatibility complex (MHC) class II, and TNF-α)." (PMID 34341329, 2021). "In murine models, Metformin increased the number of infiltrating CD8+ Tem-Cells and IL-10+ T-regs in tumour transplanted mice." (PMID 34960140, 2021). "A driving force in this cascade is tumor cell-derived IL-10 and M-CSF, which attracts and modifies circulating lymphocytes in the TME to secrete Gas6 into the TME." (PMID 35127700, 2021). "On the other hand, a significant decrease in tumor-progressive cytokines, including IL-10 and IL-4, from spleen cells treated with TEX was identified in the TEXomiR group compared to both the TEX and PBS groups." (PMID 33987190, 2021). "IL-10 also increases the expression of activation and cytotoxicity-related genes in NK cells and promotes tumor lysis by NK cells." (PMID 33708210, 2021). "In the presence of both C-7 and autologous PBMC, increased levels of IL-10 and IL-6 were found compared to the tumor alone (p = 0.002 and p = 0.004, respectively) and the “tumor + C-7” conditions (p = 0.032 and p = 0.025, respectively)." (PMID 34771609, 2021). "The cocktail included L-lactate, adenosine, TGF-β, IL-10, prostaglandin E2, and G-CSF, in an attempt to mimic the tumor environment." (PMID 34447377, 2021). "In contrast, M2 TAMs suppress the immune response via the secretion of TGF‐β, IL‐10, and arginase 1 and stimulate tumor growth through the secretion of IL‐17, IL‐23, and pro‐angiogenic factors." (PMID 33252831, 2021). "At the tumor site, a complex interplay occurs between TAM, malignant cells and stromal cells, in which stroma-derived and tumor-derived factors, such as IL4, IL-10, IL-13 and TGF-β, cause a shift towards M2 polarization." (PMID 34298810, 2021). "The immunosuppression process is evidenced by the presence of the cytokine IL-10, which plays an important role in the tumor microenvironment by decreasing the cytotoxic immune response." (PMID 34335758, 2021). "In contrast, over expression of IL-10 protected from carcinogenic and enhanced tumor immune surveillance through the activation of intratumoral antigen-presenting molecules, cytotoxic CD8+, and IFN-γ." (PMID 34572719, 2021). "Then, PDCD4 suppressed anti-inflammatory mediators such as IL-10, which creates a proinflammatory tumor microenvironment, thus retarding tumor growth." (PMID 34888227, 2021). "In fact, HRSCs produce Th-2 and T-reg chemoattractants, including CCL17/TARC, CCL22, CCL5, IL-4, IL-5, IL-10 and IL-13 and induce a functional reprogramming of tumour-infiltrating T cells skewing CD4+ differentiation toward Th-2 and T-reg phenotypes." (PMID 34298847, 2021). "In a similar manner, tumor-induced human IL-10-producing B cells or plasmablasts have been described to suppress IFN-γ and GrB expression by CD8+ T cells, as well as pro-inflammatory cytokines secreted by CD4+ T cells." (PMID 33995344, 2021). "A triple combination therapy of anti-IL-10, tumor peptides and Poly I:C, was compared to tumor peptides +/- Poly I:C, types of therapy already known to promote anti-tumor immunity." (PMID 34691085, 2021). "EcN associates with Galunisertib through increasing the levels of IFN‐γ+ CD8+ cells and DCs in tumor‐draining lymph modes along with attenuating Foxp3+ Tregs and IL‐10 in tumors." (PMID 34026439, 2021). "T-cell senescence is believed to be an alternative mechanism of immune evasion utilized by malignant cells for tumor development, as senescent T cells were shown to be an important source of immunosuppressive cytokines, such as IL-10 and TGF-β." (PMID 34502204, 2021). "Previous studies have demonstrated that engagement of TIGIT with CD155 can deliver an inhibitory signal, leading to increased secretion of IL-10 in tumor cells and dendritic cells (DCs)." (PMID 33581644, 2021).
tumor (continued). "We have also previously observed a similar (albeit “incomplete”) shift in macrophage phenotype (based on expression of TNF and IL-10) during tumor growth in young female C57BL/6J mice with mesothelioma tumors." (PMID 33441138, 2021). "Since IL-10 is generally recognized as an immunosuppressive cytokine, IL-10 is known to be able to facilitate tumor immune escape by reducing the antitumor immune response in the tumor immune microenvironment." (PMID 33767709, 2021). "In particular, they exert an immunosuppressive function both through the direct production of TGF-beta, ROS, IL-10 and peroxynitrite and through the indirect induction of T-reg differentiation in lymphocytes, thus promoting tumour growth and survival." (PMID 34298847, 2021). "MDSCs secrete TGF-β and IL-10 that have direct immunosuppressive effects and induce Treg expansion, which suppressed tumor-specific T cell responses." (PMID 34867958, 2021). "On the other hand, the anti-inflammatory IL-10 expression was increased only in the primary tumor treated with LyeTx I-b." (PMID 34572719, 2021). "IL-10 is considered an anti-inflammatory cytokine capable of inhibiting the release of inflammatory cytokines playing an important role in anti-tumor immunoresponse." (PMID 33679798, 2021). "Conversely, M2 macrophages express high levels of IL-10 and scavenger receptor, can promote tumor angiogenesis and immunosuppression, facilitating tumor angiogenesis and immunologic suppression." (PMID 34656118, 2021). "The IL10+Ad-hTERT induced almost sevenfold or fivefold increase in IFN-γ level compared with the PBS control group in LLC or B16F10 tumor-bearing mice respectively." (PMID 33717103, 2021). "Tumor-secreted factors, such as IL-4, IL-10, and M-CSF, can induce the polarization of macrophages into M2-like tumor-associated macrophages (M2-like TAMs)." (PMID 33959512, 2021). "For example, type-2 (M2) TAMs express multiple immunosuppressive and tumor promoting factors, such as prostaglandin E2, vesicular endothelial growth factor, and IL-10, leading to suppressed anti-tumor responses." (PMID 34576180, 2021). "Studies have shown that increasing IL-10 serum concentration to a certain level can enhance the anti-tumor effect of CD8+ T cells, which has been verified in various solid tumors such as pancreatic cancer, lung cancer, and kidney cancer." (PMID 34625124, 2021). "The production of IL-10 by the CD163+ macrophages suggested that ST11 K. pneumoniae promoted the accumulation of M2-like tumor-associated macrophages in the lumens of adenomatous crypts." (PMID 34606408, 2021). "The engagement of PD-L1 with PD-1 of T cells leads to T-cell dysfunction, exhaustion, neutralization, and interleukin-10 (IL-10) production in a tumor mass." (PMID 34305619, 2021). "More recently, IL-10+ B cells and IL-10+ plasmablasts have been recovered from tumor or tumor draining lymph nodes, while cancer patients show increased circulating IL-10+ Bregs." (PMID 33995344, 2021). "These opsonized tumor cells were then co-cultured with naïve unstimulated human monocyte-derived macrophages (MDMs) (M0) or M-CSF/IL-10-treated human MDMs used to mimic TAMs found in the tumor microenvironment." (PMID 33924378, 2021). "TAMs suppress anti-tumor immunity by the secretion of chemokines and cytokines such as IL-1 and IL-10, proangiogenic factors such as VEGF and EGF, and MMP including MMP-9." (PMID 35008212, 2021). "The Th2 cells produce IL-4 and IL-10 and inhibit the host immune system, hence having a role in promoting tumor growth." (PMID 35265097, 2021). "An increased level of IL12p70 and IFN-γ, decreased levels of immunosuppressive IL-10 and IL-4, and elevated T-lymphocyte infiltration in tumor tissues in TEXomiR-treated mice do suggest that TEXomiR treatment elicits strong immunomodulatory effects." (PMID 33987190, 2021). "On the other hand, IL-10 exerts anti-tumor activity by enhancing the immune-stimulatory effect of CD8+ T cell." (PMID 35059436, 2021).
tumor (continued). "Typically, the TME is characterized by presenting high levels of the anti-inflammatory, immunosuppressive cytokine IL-10, which facilitates tumor expansion." (PMID 33669271, 2021). "Glioblastoma cells block astrocytic anti-tumor responses partially by releasing IL-10 and IFN-γ resulting in tumor growth." (PMID 34949203, 2021). "M2-type cells are mainly activated by Th2-related cytokines (e.g. IL-4, IL-10, and IL-13) and suppress T cell responses as well as promote tumor cell growth, invasion, and metastasis." (PMID 34965886, 2021). "IL-10 is produced by multiple different cells in the tumor microenvironment (TME) including Tregs, tumor-associated macrophages (TAM) and cancer cells." (PMID 33717081, 2021). "Breg have been implicated in the clinical progression of various types of cancers and have been proposed to promote tumor growth through IL-10 production.To date, relatively little is known about Breg differentiation in the lung TME." (PMID 34867973, 2021). "IL-10 and TGF-β secreted by tumor-associated regulatory T cells restrict the function of CD8+ effector T cells and the maturation of DCs, thus further inhibiting innate immunity and adaptive immunity." (PMID 34326876, 2021). "After co-culturing with PDA cells, GARP KO M1-like macrophages failed to increase the expression of IL-10, suggesting the tumor-induced IL-10 overexpression in WT M1-like macrophages is also attributed to a post-transcriptional mechanism." (PMID 34711804, 2021). "Once established, tumor-derived factors drive macrophages towards an immunosuppressive phenotype mediated through IL-4, IL-10 and TGF-β release similar to reparative macrophages during injury repair." (PMID 33441138, 2021). "IL10 was observed to activate JAK/STAT3 signaling and induce EGFR expression, which in turn promoted IL10 expression via PI3K/nucleolin signaling to facilitate a feedforward loop that supports tumor development." (PMID 34944848, 2021). "Several tumor-secreting cytokines, including IL-6, IL-10 and TGF-b1, are essential for Treg differentiation." (PMID 35111682, 2021). "Polymeric systems decreased the IL-10 concentration and normalized the IL-17 concentration in tumor-bearing rats." (PMID 34443443, 2021). "IL-10 is an anti-inflammatory cytokine and its serum levels are negatively related to the tumor prognosis." (PMID 35059436, 2021). "Hypoxia indirectly regulates the immune response and cell invasion into the tumor by increasing regulatory cytokines (IL-10, TGF-β) and decreasing cell adhesion molecules on tumor-associated blood vessels." (PMID 34150739, 2021). "CTLA-4-expressing CD14+ dendritic cells (DCs) are also associated with the attenuation of anti-tumor T cell responses due to indoleamine 2, 3-dioxygenase (IDO) and IL-10 production." (PMID 34575463, 2021). "In a murine model, TNF-α, IFN-γ, IL-1, and IL-10 were demonstrated to increase significantly after a cycle of cryoablation of tumor tissue in an experimental setting." (PMID 34830949, 2021). "ANG-2, secreted from tumor and vasculature cells, can enhance IL-10 and mannose receptor expression, while decreasing that of TNF-α and IL-12, thereby weakening TAM anti-tumor activity under hypoxic conditions." (PMID 34603327, 2021). "In a recent study, we have shown that intratumoral injection of the caerin 1.1/1.9 mixture significantly prolonged the survival time of TC-1 tumour-bearing mice that were immunised with an HPV16 E7 peptide-based vaccine along with IL-10 and PD-1 blockade." (PMID 34858827, 2021). "IL-10 is widely expressed in the tumor microenvironment by tumor cells as well as various innate immune cells such as macrophages and dendritic cells." (PMID 34769278, 2021). "Regulatory B cells (Breg) are IL-10 producing subsets of B cells that contribute to immunosuppression in the tumor microenvironment (TME)." (PMID 34867973, 2021).